SSB (small RNA binding exonuclease protection factor La)
Diseases named in the same sentence as SSB in open-access papers (continued):
Sharing a sentence is not in itself a finding about the gene and the disease.
mixed connective tissue disease (6 papers, 2007 to 2025). Mixed connective tissue disease (MCTD) is a rare autoimmune disorder that is characterized by features commonly seen in three different connective tissue disorders: systemic lupus erythematosus, scleroderma, and polymyositis. "High antibody titers to nuclear ribonuclear protein is suggestive of mixed connective tissue disease (MCTD), especially in the absence of other autoimmune antibodies such as anti-Smith, anti-SSA/ro and SSB/la antibodies." (PMID 36447819, 2022).
nephritis (6 papers, 2017 to 2023). Inflammation of renal tissue. "As might be expected, the RF-high group had increased frequency of anti-Ro/SSA and anti-La/SSB antibodies and a reduced frequency of nephritis." (PMID 37516862, 2023). "The frequency of nephritis was similar and relatively low in both RF-IgM/SSA/SSB and SSA/SSB+ subgroups (20 and 21% respectively) while higher in other subgroups (>40%)." (PMID 31156624, 2019). "They reported a synchronized decrease in the incidence of anti-SSA and anti-nRNP and a lack of anti-SSB autoantibodies; also, male patients with nephritis have a large rise in dsDNA." (PMID 37016193, 2023). "Beside the SSA/SSB antibody profile, these clusters were not connected to clinical disease manifestations such as nephritis or survival." (PMID 33037003, 2021).
Nephropathy (6 papers, 2014 to 2024). A nonspecific term referring to disease or damage of the kidneys. "Renal disorder was associated with the presence of anti-dsDNA (P < 0.001) and anti-SSB (P = 0.006) antibodies." (PMID 37344560, 2023). "Some factors were reported to be positively associated with kidney disease in pSS, including ANA, anti-SSA, anti-SSB, RF, low C3/C4, urea, creatinine, cystatin C, β2-microglobulin, etc.." (PMID 37735697, 2023). "Patients with renal disease were found to have higher serum levels of prealbumin, anti-scl-70, RF, anti-extractable nuclear antigen (ENA), anti-SSB, anti-SM, urea, creatinine, cystatin C, α1-microglobulin (α1-MG), serum β2-microglobulin, and other molecules." (PMID 33042142, 2020). "In this study, we found the associations between anti-SSA antibody and PAH, between anti-SSB antibody and hematological involvement, and between anti-SSA antibody and a lower prevalence of nephropathy." (PMID 24864270, 2014). "Although researchers did not focus specifically on renal disease, they found higher rates of systemic involvement in patients with anti-SSB and parotid enlargement or purpura at presentation." (PMID 33042142, 2020). "In addition, we found that anti-SSB antibody correlated to ESR, lower levels of IgA and Complement C4, lower Alb concentrations, lower prevalence of appendicular rash, higher prevalence of renal disorder and more serious hepatic damage." (PMID 37344560, 2023).
cryoglobulinemia (5 papers, 2015 to 2024). Cryoglobulinemia is a type of vasculitis that is caused by abnormal proteins (antibodies) in the blood called 'cryoglobulins.' At cold temperatures, these proteins become solid or gel-like, which can block blood vessels and cause a variety of health problems. "Most children show positive antinuclear antibodies (ANA) and anti-SSA/Ro, and, to a lesser extent, anti-SSB/La and rheumatoid factor (RF) are also frequently found, while low complement levels and cryoglobulinemia are less frequent." (PMID 38190091, 2024). "CVL in pSS were associated with laboratory findings, such as the presence of anti-Ro/SSA and anti-La/SSB antibodies, monoclonal gammopathy, cryoglobulinemia and hypocomplementemia." (PMID 36233393, 2022). "Serological and histopathological features independently predicting NHL development were RF, anti-Ro/SSA or/and anti-La/SSB positivity, monoclonal gammopathy, C4 hypocomplementemia, cryoglobulinemia, and Tarpley score in the MSG biopsy ≥3." (PMID 27336863, 2016).
polymyositis (5 papers, 2007 to 2025). A rare idiopathic inflammatory myopathy characterized by symmetric proximal muscle weakness and elevated muscle enzymes. "Additionally, patients were tested for anti‐Sjogren's syndrome A (SSA Ro), anti‐Sjogren's syndrome B (SSB La), RNP/Sm, Polymyositis antibodies (Jo‐1), Sm, Scleroderma antibodies (Scl‐70), chromatin, centromere, histone, and RNA polymerase III within an anti‐ENA panel." (PMID 41131836, 2025).
rheumatic diseases (5 papers, 2011 to 2024). "Traditionally, SS can be distinguished into primary and secondary disease: the primary disease can be diagnosed in a patient with sicca syndrome in the absence of other underlying rheumatic diseases, and is often associated with anti-Ro/SS-A and anti-La/SSB autoantibodies." (PMID 34208031, 2021). "For all pregnant women with rheumatic diseases and positive anti-Ro/SSA and/or anti-La/SSB antibodies, HCQ treatment is conditionally recommended when they have low disease activity." (PMID 38167489, 2024).
alopecia (4 papers, 2020 to 2026). Hair loss usually from the scalp. "On the contrary, plasma levels of IL‐38 did not relate to rash; alopecia; fever; reduced platelet; antibodies ANA, anti‐Sm, anti‐SSA, anti‐SSB and anti‐rRNA; expression of IgA, IgM and IgG; or ESR." (PMID 33079487, 2020).
Heart block (4 papers, 2012 to 2026). Impaired conduction of cardiac impulse occurring anywhere along the conduction pathway. "The prenatal evaluation focuses not only on the maternal screening for anti-Ro/SSA and anti-La/SSB antibodies, but also on in utero surveillance for heart block." (PMID 32674462, 2020).
interstitial lung disease (4 papers, 2020 to 2024). A diverse group of lung diseases that affect the lung parenchyma. "The reported presence of anti-Ro/SSA and anti-La/SSB in SS patients with interstitial lung disease is highly variable." (PMID 32630417, 2020). "The proportion of CD161+CD56+ NK cells in pSS patients with decayed tooth, fatigue, arthralgia, skin involvement, primary biliary cirrhosis, interstitial lung disease, anti‐SSA/Ro60 positive, anti‐SSB positive and high IgG was lower than that in negative patients." (PMID 38577997, 2024).
monoclonal gammopathy (4 papers, 2016 to 2025). A condition characterized by the abnormal presence of monoclonal immunoglobulins in the blood or urine. "Salivary gland enlargement (SGE), lymphadenopathy, Raynaud phenomenon, anti-Ro/SSA or/and anti-La/SSB autoantibodies, rheumatoid factor (RF) positivity, monoclonal gammopathy, and C4 hypocomplementemia were shown to be independent predictors for NHL development." (PMID 27336863, 2016). "Some developmental scores for lymphoma have been established, and they include salivary gland enlargement, RF positivity, lymphadenopathy, monoclonal gammopathy, Raynaud’s phenomenon, anti-Ro/SSA and/or anti-La/SSB autoantibodies, and low C4." (PMID 40291311, 2025).
type 1 diabetes (4 papers, 2016 to 2021). "non-obese diabetic (NOD) mice manifest not only type I diabetes (T1D) but SjS-like autoimmune endocrinopathy as well and also present a few hallmark autoantibodies like ANA, anti-SSA/Ro, anti-SSB/La, anti-a-fodrin, etc.." (PMID 29881381, 2018).
viral infection (4 papers, 2013 to 2024). "Many studies have suggested that the autoantigens triggering production of SSA and SSB autoantibodies, Ro and La, are released locally in exocrine tissue due to early disease triggers (viral infection, ER stress, apoptosis) where they can be processed in TLS to generate autoantibodies." (PMID 39936155, 2024).
atrioventricular block (3 papers, 2020 to 2025). A heart block that is initiated in the atrioventricular node. "The laboratory characteristics, such as anti dsDNA, are considered as indicators of disease activity level and poor prognostic of SLE, and anti SSA/SSB antibodies are verified to be the cause of fetal atrioventricular block." (PMID 39039448, 2024). "Maternal anti-SSA and anti-SSB antibodies can pass through the placenta during pregnancy and affect the fetal heart, resulting in structural or rhythmic abnormalities, such as atrioventricular block, EFE, sinus bradycardia, and delayed dilated cardiomyopathy." (PMID 40589968, 2025).
Hashimoto thyroiditis (3 papers, 2016). An autoimmune disorder caused by the production of autoantibodies against thyroid tissue. "The risk of delivering a child with CCHB is higher among women who are anti-SSA/Ro or anti-SSB/La positive and in those with autoimmune hypothyroidism." (PMID 27756424, 2016).
lung disease (3 papers, 2013 to 2024). "The pediatric patient presented here demonstrates multiple manifestations of SS, including recurrent parotitis, IIH, and lung disease with positive ANA, SSA and SSB antibodies, without sicca symptoms." (PMID 36384806, 2022).
overlap syndrome (3 papers, 2008 to 2025). "Given that anti-SSB/La antibodies are less commonly detected in isolated myositis, their predictive value in overlap syndromes warrants further prospective validation." (PMID 40995369, 2025). "One patient presented with overlap syndrome characterized by ANA, anti-Scl70, anti-SSA, and anti-SSB positivity with a long-lasting disease (22 years) and was on hydroxychloroquine and golimumab." (PMID 34203626, 2021).
parotitis (3 papers, 2020 to 2022). Inflammation of the parotid glands. "In contrast, positive anti-SSB and positive RF were independent risk factors of parotitis in patients with C-pSS." (PMID 36683822, 2022). "We observed that a higher FS of LSG biopsy, ANA titer ≥ 1:320, positive RF, anti-SSA/Ro60, and anti-SSB values were more likely to occur in patients with parotitis, and that positive RF and anti-SSB were independent risk factors for parotitis in pSS." (PMID 36683822, 2022). "Immunological markers may play a vital role in parotitis development in pSS, as positive RF and anti-SSB were independent risk factors for parotitis in pSS." (PMID 36683822, 2022). "Furthermore, positive anti-SSB (P = 0.012) and positive RF (P = 0.028) were independent risk factors for parotitis in patients with C-pSS." (PMID 36683822, 2022). "In the parotitis group, higher ANA titers (P = 0.027), higher focus scores on labial gland biopsy (P = 0.024), and positive RF (P = 0.001), anti-SSA/Ro60 (P = 0.003), and anti-SSB (P = 0.001) were observed more frequently." (PMID 36683822, 2022). "Anti-Ro antibody is negative, only 1 case has parotitis, parotid ultrasound shows hypoechoic focus, and anti-LA/SSB antibody indicates positive." (PMID 32832568, 2020).
pericarditis (3 papers, 2014 to 2024). An inflammatory process affecting the pericardium. "Anti-SSB body was found to be associated with hematological disorder, proteinuria, malar rash, and pericarditis." (PMID 24864270, 2014). "Moreover, the authors analyzed the contribution of SLE antibody to the development of this specific manifestation, showing a significant association between the risk to develop pericarditis and anti-La/SSB positivity (OR = 2.65)." (PMID 26798662, 2015).
autoimmune thyroid disease (2 papers, 2020 to 2023). Inflammatory disease of the thyroid gland due to autoimmune responses leading to lymphocytic infiltration of the gland. "In addition, the non-progression group had higher rates of autoimmune thyroid disease (ATD) though the difference failed to reach statistical significance, as patients with ATD were observed to have a lower prevalence of SSA and SSB antibodies but similar cumulative SS activity." (PMID 37735697, 2023).
COVID-19 (2 papers, 2022 to 2023). A disease caused by infection with severe acute respiratory syndrome coronavirus 2. "Similar findings were also observed in patients with COVID-19, in which significantly elevated levels of anti-SSA/Ro52 and anti-SSB/La were seen." (PMID 37676726, 2023). "The sera from patients with COVID-19 sera showed increased ANA (i.e., anti-SSA [Sjögren’s-syndrome-related antigen A]/anti-Ro52 and anti-SSB [SS-antigen B]/anti-La)." (PMID 37676726, 2023). "A small number of COVID-19 patients had antibodies against Ro52, Ro60, and La comprising the SSA and SSB rheumatological autoantigens." (PMID 35360001, 2022).
endothelial dysfunction (2 papers, 2022 to 2023). In vascular diseases, endothelial dysfunction is a systemic pathological state of the endothelium (the inner lining of blood vessels) and can be broadly defined as an imbalance between vasodilating and vasoconstricting substances produced by (or acting on) the endothelium. "The positivity of anti-SSA/Ro and -SSB/La antibodies, two well-known markers of the disease and generally associated with systemic manifestations, may correlate with endothelial dysfunction and with an increase in the intima-media thickness." (PMID 35634284, 2022). "Endothelial dysfunction (expressed as FMD%) was correlated with focus score, ESSDAI, levels of anti-SSA and anti-SSB antibodies, beta-2 microglobulin, IL-6, and TNF-α, with statistical significance." (PMID 37762225, 2023).
infertile (2 papers, 2022 to 2025). "Incorporating anti-Ro/SSA and anti-La/SSB autoantibody testing into infertility screening and multidisciplinary counseling within IVF protocols permits earlier risk identification, improved prenatal surveillance, and informed planning for future pregnancies." (PMID 41465829, 2025).
influenza (2 papers, 2019 to 2021). An acute viral infection of the respiratory tract, occurring in isolated cases, in epidemics, or in pandemics; it is caused by serologically different strains of viruses (influenzaviruses) designated A, B, and C, has a 3-day incubation period, and usually lasts for 3 to 10 days. "Yet, vaccinated SS patients exhibit important long-term (one year) changes, including a significant increase in the levels of anti-Ro/SSa and anti-La/SSB, which has been shown to be associated with an increase in B-cell activation in SS patients after influenza vaccination." (PMID 34136315, 2021).
MALT lymphoma (2 papers, 2021 to 2024). An indolent, extranodal type of non-Hodgkin lymphoma composed of small B-lymphocytes (centrocyte-like cells). "A patient diagnosed with MALT lymphoma displayed increased levels of C3, C4, rheumatoid factor, anti-SSA/SSB antibodies, anti-Scl-70 antibodies, and anti-Ro-52 antibodies." (PMID 38959275, 2024). "Two SSA and SSB antibody negative patients developed non-MALT lymphomas at follow-up, aged >70 years (73 and 82, respectively)." (PMID 34335613, 2021).
pericardial effusion (2 papers, 2018 to 2024). Fluid collection within the pericardial sac, usually due to inflammation. "If the mother tests positive for anti-SSA/SSB antibodies, serial echocardiograms should be performed to detect early fetal abnormalities, such as PACs or pericardial effusion, which may precede a total AV block." (PMID 39144470, 2024).
sarcoidosis (2 papers, 2024). Sarcoidosis is a multisystemic disorder of unknown cause characterized by the formation of immune granulomas in involved organs. "Similarly, autoimmune features have been reported in sarcoidosis, including the presence of autoantibodies directed against Ro52, Ro60, SSB, Rib-P, CCP, and β2-glycoprotein." (PMID 39309852, 2024).
venous thromboembolism (2 papers, 2019 to 2022). Occlusion of the lumen of a vein by a thrombus that has migrated from a distal site via the blood stream. "We saw a higher prevalence of anti-SSB/La positivity in pSS patients with MI (p = 0.017), whilst we did not see an association with venous thromboembolism." (PMID 36588566, 2022).
Anxiety (1 paper, 2025). Intense feelings of nervousness, tension, or panic often arise in response to interpersonal stresses. "Third and finally, the study revealed clinically relevant relationships between variables—for example, the association between trait anxiety and SSA as well as SSB autoantibodies." (PMID 40530052, 2025).
Arthralgia (1 paper, 2023). "Arthralgias may appear concurrently with the sicca symptoms and correlate with anti-Ro/SSA anti-La/SSB antibodies positivity." (PMID 37373950, 2023).
arthrosis (1 paper, 2024). "Higher positive rates of anti-SSB and higher incidence of dry cough, dyspnea, and arthrosis symptoms were shown in pSS-ILD patients than in the pSS-N-ILD cases." (PMID 39234569, 2024).
Bradycardia (1 paper, 2025). A slower than normal heart rate (in adults, slower than 60 beats per minute). "The transplacental migration of anti-Ro/SSA and anti-La/SSB antibodies damages the fetal cardiac system, leading to sustained bradycardia, cardiomyopathy, fetal hydrops, and intrauterine fetal demise." (PMID 41465829, 2025).
cardiac arrhythmia (1 paper, 2023). Any disturbances of the normal rhythmic beating of the heart or MYOCARDIAL CONTRACTION. "Voltage-gated L-type Ca2+ channels, specifically Cav1.3, play a key role in the pathophysiology of cardiac arrhythmias in the presence of autoimmune antibodies such as anti-Ro/SSA and anti-La/SSB." (PMID 37025382, 2023).
cholestasis (1 paper, 2011). Impairment of the bile flow caused by obstruction within the liver, or outside the liver in the bile duct system. "The diagnosis of NLE liver disease requires that bilirubin and liver enzyme levels are consistent with cholestasis and hepatitis, along with detection in the infant of maternal antibodies to SSA/Ro and/or SSB/La." (PMID 20864789, 2011).
cutaneous lupus erythematosus (1 paper, 2021). An autoimmune disorder that manifests as different lupus-specific skin disorders; it can occur with systemic lupus erythematosus, or as a singular disease. "We present a female neonate with MAS born to a mother who had cutaneous lupus erythematosus with circulating anti-nuclear antibodies (ANA), anti-SSA, anti-SSB and anti-extractable nuclear antigen (anti-ENA) antibodies." (PMID 33568193, 2021).
encephalitis (1 paper, 2022). An acute inflammatory process affecting the brain parenchyma. "Among cases with anti-NMDAR encephalitis, 6 (9.38%) patients were an anti-SmRNP antibody; 6 (9.38%) patients for an anti-SSA60 antibody; 4 (6.25%) patients for an anti-SSA52 antibody; 2 (3.13%) patients for an anti-SSB antibody." (PMID 36313496, 2022).
fibromyalgia (1 paper, 2015). A chronic disorder of unknown etiology characterized by pain, stiffness, and tenderness in the muscles of neck, shoulders, back, hips, arms, and legs. "Patients with SS were older, and showed more severe lachrymal and salivary dysfunctions, greater frequency of fibromyalgia, anti-nuclear antibodies (ANA), anti-SSA-Ro, and anti-SSB-La." (PMID 25887888, 2015).
H1N1 influenza (1 paper, 2018). "In a recent study, adjuvanted H1N1 influenza vaccination of untreated pSS patients resulted in higher specific IgG titers compared to healthy controls, and autoantibody (Ro/SSA and La/SSB) titers increased." (PMID 30886963, 2018).
multiple myeloma (1 paper, 2025). "The risk of MGUS seems restricted to patients with anti-Ro/SSA and anti-La/SSB autoantibodies; however, studies on its evolution to multiple myeloma are limited." (PMID 40416966, 2025).
non-alcoholic fatty liver disease (1 paper, 2022). "A subgroup of patients with anti-SSA and/or anti-SSB coexists with SjS was also identified; patients with only AMA and/or AMA-M2-positive with a benign clinical outcome and relatively high complication of non-alcoholic fatty liver disease (NAFLD) were also identified." (PMID 36685575, 2022).
Pancytopenia (1 paper, 2022). An abnormal reduction in numbers of all blood cell types (red blood cells, white blood cells, and platelets). "ALT107.6u/l,AST174.5u/l,Pancytopenia,anti-SSA, anti-SSB, anti-ANA and anti-cardiolipin antibodies were positive, hypocomplementemia." (PMID 35585974, 2022). "Pancytopenia, anti-SSA, anti-SSB, anti-ANA and anti-cardiolipin antibodies were positive,hypocomplementemia." (PMID 35585974, 2022). "From November 29, 2016, to April 6, 2018, rituximab was successively administered 4 times; the patient was in a stable condition, but still with pancytopenia, cirrhosis, and continuous positive anti-SSA and anti-SSB antibodies." (PMID 35585974, 2022).